S100A16 (S100 calcium binding protein A16)
Diseases named in the same sentence as S100A16 in open-access papers (continued):
Sharing a sentence is not in itself a finding about the gene and the disease.
glioma (7 papers, 2021 to 2025). A benign or malignant brain and spinal cord tumor that arises from glial cells (astrocytes, oligodendrocytes, ependymal cells). "Among these genes, we identified S100A16 using multiple criteria, including its association with glioma, functional validation, and overall survival analysis." (PMID 36224471, 2022). "Our bioinformatic analysis implied that the Hippo signaling pathway, MTOR pathway, WNT pathway et.al might be implicated in glioma malignant progression regulated by S100A16." (PMID 37151881, 2023). "In addition, S100A16 was significantly associated with glioma patients' prognosis, meaning that the survival time of patients with high-S100A16 expression was greatly shorter than those with low S100A16." (PMID 37151881, 2023). "Our study aimed to explore the biological function and possible mechanism of S100A16 in the progression of glioma." (PMID 37151881, 2023). "The results indicated that S100A16 predicted poor prognosis in glioma by promoting cell proliferation, migration and invasive abilities via inhibiting LATS1 expression in the Hippo pathway." (PMID 37151881, 2023). "Survival analysis showed that high S100A16 expression significantly shortened the survival time of glioma patients, especially for GBM patients." (PMID 37151881, 2023). "In conclusion, we discovered that S100A16 was highly expressed in glioma and related to prognostic survival." (PMID 37151881, 2023). "Considering that S100A16 is abundantly expressed in the nervous system, and glioma is the most frequent CNS cancer, it is essential to elucidate the potential function and mechanism of S100A16 in glioma." (PMID 37151881, 2023). "Next, we analyzed S100A16 expression in glioma U87, U251, T98G, LN229, A172, SW1738, N3 cells and control NHA cells by western blot, and showed different levels of S100A16 proteins." (PMID 37151881, 2023). "In this study, we first found that S100A16 expression differed between normal brain and glioma tissues, which varied across tumor types, based on GEPIA database." (PMID 37151881, 2023). "IHC assay also confirmed S100A16 overexpression in glioma, and its positivity was observed in the cytoplasm and nuclei of glioma cells." (PMID 37151881, 2023). "Taken together, these findings indicated that S100A16 promoted glioma cells' proliferation, migration, and invasion." (PMID 37151881, 2023). "We further conducted functional experiments to investigate the significance of S100A16 in glioma progression." (PMID 37151881, 2023). "It was first established that S100A16 upregulation greatly enhanced glioma proliferation, migration and invasion." (PMID 37151881, 2023). "Our study established a critical role of S100A16 in glioma development, and offered a new direction for glioma diagnosis, therapy and prognosis." (PMID 37151881, 2023). "To prove the promoting effect of S100A16 in vivo, we infected glioma cells with S100A16 shRNA or cDNA lentivirus, and constructed the subcutaneous or orthotopic animal model." (PMID 37151881, 2023). "In this study, we aimed to gain a better understanding of S100A16's biological function and molecular mechanism in glioma progression by using bioinformatics analysis, in vitro and in vivo functional tests." (PMID 37151881, 2023). "S100A16 overexpression promoted the proliferation, invasion and migration of glioma cells, and the tumor formation of nude mice." (PMID 37151881, 2023). "To validate the bioinformatic data, we analyzed S100A16 expression in clinical samples from 5 NBTs and 20 glioma tissues of different grades." (PMID 37151881, 2023). "According to the CGGA database, S100A16 closely correlates with the survival rate of patients with primary gliomas." (PMID 36224471, 2022). "Firstly, the S100A11, S100A16, and S100B expression levels were significantly upregulated in glioma tissues than in normal controls from GEPIA database." (PMID 34712325, 2021). "Glioma tissues were collected to examine S100A16 expression levels." (PMID 37151881, 2023).
glioma (continued). "In our study, S100A16 was shown to have a promotive impact on glioma proliferation, invasion and metastasis, which might be achieved by knockdown of LATS1." (PMID 37151881, 2023). "Moreover, transwell and wound healing assays suggested that sh-LATS1 reversed the inhibitory impact of sh-S100A16 on glioma migration and invasion in U251 cells." (PMID 37151881, 2023). "The potential mechanisms of S100A16-mediated glioma development require deep exploration." (PMID 37151881, 2023). "This implies that S100A16 may have a potential role in promoting CUL4ADCAF-mediated ubiquitination of LATS1 in glioma." (PMID 37151881, 2023). "Therefore, we examined the impact of S100A16 on this pathway's core members in glioma cells by Western blot." (PMID 37151881, 2023). "Consequently, these data revealed a new insight into glioma pathogenesis and identified S100A16 as a prospective molecular target for glioma patients' diagnosis, treatment and prognosis." (PMID 37151881, 2023). "In addition, western blot suggested that S100A16 protein expression was evaluated with increasing glioma grade." (PMID 37151881, 2023). "It revealed a new mechanism by which S100A16 promoted the development and progression of glioma." (PMID 37151881, 2023). "These suggested that S100A16 may be highly related to Hippo pathway in glioma." (PMID 37151881, 2023). "Bioinformatics in our study predicted that S100A16 may regulate Hippo signaling pathway in glioma." (PMID 37151881, 2023). "S100A16 could be a novel biomarker and treatment option for glioma patients." (PMID 37151881, 2023). "These suggested that S100A16 might act as an oncogene promoter in glioma." (PMID 37151881, 2023). "Specifically, S100A8 and S100A9 were expressed in myeloid cells, S100A10 and S100A11 in various cell types, especially in glioma tumor cells, and S100A13 and S100A16 in vascular cells." (PMID 39744679, 2025). "To further confirm that S100A16 regulates LATS1 protein levels through CUL4A-mediated ubiquitination, we transfected CUL4A siRNA or cDNA into glioma cells pre-treated with MG132." (PMID 37151881, 2023). "In total, these findings suggest that S100A16 inhibited Hippo signaling pathway, thus regulating YAP behavior and cellular distribution in glioma cells." (PMID 37151881, 2023). "In our previous study, we developed an S100 family-based prognostic signature consisting of five genes of S100A11, S100A16, S100B, S100PBP and S100A13 for glioma patients." (PMID 37151881, 2023). "In human brain tissues, S100A16 is highly expressed in glioma relative to non-neoplastic brain tissues, which was also verified in the TCGA, CGGA and GEO databases." (PMID 37151881, 2023). "Furthermore, we analyzed S100A16 expression and clinical information of 325 glioma patients based on the CGGA database and showed that the level of S100A16 expression increased with the grade of malignancy, with the highest expression in GBM patients." (PMID 37151881, 2023). "For the GEPIA-derived cohort, the expression levels of S100A11, S100A16, and S100B in low-grade glioma (LGG) and GBM samples increased compared with those in noncarcinoma samples, while S10013 in LGG tissue was upregulated in normal tissues." (PMID 34712325, 2021). "We also found that S100A16 could be a key regulator of WNT pathway in acute renal injury 26, but their association in glioma has not been reported." (PMID 37151881, 2023). "However, S100A16's molecular mechanism and function in human glioma have not been well understood." (PMID 37151881, 2023).
ovarian cancer (7 papers, 2015 to 2023). A primary or metastatic malignant neoplasm involving the ovary. "Our results indicated that higher level of S100A16 predicted worse OS in ovarian cancer, especially in grade II, grade III, and stage III EOC patients." (PMID 30558666, 2018). "Whereas, some other S100 family members, including S100A3, S100A5, S100A7, S100A7A, S100A8, S100A16 and S100G are less reported in ovarian carcinoma." (PMID 30558666, 2018). "Moreover, among secreted factors, RP enabled greater identification of S100A16, a member of the serpin family, which plays an important role in ovarian function and has prognostic value in ovarian cancer." (PMID 33266304, 2020). "Additionally, progressive down-regulation of S100A16 as found in CRC, prostate and ovarian cancers demonstrates a broader relevance for S100A16 in the process of tumorigenesis of other human malignancies and warrants further investigation in these tumor types." (PMID 26353754, 2015).
cervical carcinoma (6 papers, 2020 to 2024). A carcinoma arising from either the exocervical squamous epithelium or the endocervical glandular epithelium. "S100A16 has been implicated in the maintenance of cancer stem‐like features in cervical carcinoma cells." (PMID 38924205, 2024). "Referencing the mRNA expression and SNP data of cervical cancer available through The Cancer Genome Atlas (TCGA) database, we analyzed S100A16 and its associated regulatory gene expression network in cervical cancer." (PMID 37978469, 2023). "Using clinical information and S100A16 gene expression level, we established univariate and multivariate Cox regression models and constructed forest plots that showed N in cervical cancer patients was associated with the risk and had a statistical difference between the groups." (PMID 37978469, 2023). "The mRNA and protein expression of stem cell markers (Oct4 and Nanog) were reduced after S100A16 silencing and the spheroid formation ability of cervical cancer cells was considerably reduced upon S100A16 knockdown." (PMID 38924205, 2024). "Our results showed that data mining can effectively elucidate the expression and gene regulatory network of S100A16 in cervical cancer, laying the foundation for further investigations into S100A16 cervical tumorigenesis." (PMID 37978469, 2023). "Regression analysis of patients in our study showed that the values of the different clinical indicators of cervical cancer and the distribution of S100A16 expression had varying degrees of contribution throughout the scoring process." (PMID 37978469, 2023). "We further explored the co-expression network of S100A16 using the expression profiles of cervical cancer patients annotated in the TCGA database." (PMID 37978469, 2023). "Our study results suggest that cervical cancer patients with high S100A16 expression were highly sensitive to drugs, such as gemcitabine and axitinib." (PMID 37978469, 2023). "In summary, S100A16 mRNA and protein were abnormally upregulated in cervical cancer, and their overexpression indicated a poor prognosis and malignant tumor progression in cervical cancer patients." (PMID 37978469, 2023). "High expression of the S100A16 protein was correlated to disease progression and prognosis of cervical cancer, and thus we investigated the hub genes and sensitivities to common chemotherapeutic drugs." (PMID 37978469, 2023). "S100A16 expression was significantly upregulated in cervical cancer specimens." (PMID 37978469, 2023). "We further screened genes co-expressed with S100A16 to hypothesize their function and relationship to the S100A16 cervical cancer phenotype." (PMID 37978469, 2023). "S100A16 can also promote the proliferation and invasion of cervical cancer cells." (PMID 33912559, 2021). "Immunohistochemical staining of cervical cancer cells and the corresponding adjacent normal healthy cervical tissue specimens (ANT) was performed to investigate whether the S100A16 protein expression was altered in the tissues of cervical cancer patients." (PMID 37978469, 2023).
prostate carcinoma (6 papers, 2016 to 2024). A carcinoma that arises from epithelial cells of the prostate gland. "Abnormal expression of S100A16 protein is implicated in the progression of breast and prostate cancer, but an inhibitor of oral cancer and acute lymphoblastic leukemia tumor cell proliferation (BMC Cancer 15:53, 2015; BMC Cancer 15:631, 2015)." (PMID 37978469, 2023). "S100A16 is a novel member of the S100 family, ubiquitously expressed in all human tissues including fat tissues and the lung and is associated with a variety of human diseases, such as inflammation disorders, prostate cancer and obesity." (PMID 26751474, 2016). "Some studies have suggested that S100A16 was involved in promoting cell proliferation, metastasis, and tumor growth in certain cancers, including prostate cancer and esophageal squamous cell carcinoma." (PMID 38710691, 2024). "Studies have shown that S100A16 activates the AKT signaling pathway in prostate cancer to promote cell invasion, metastasis, and proliferation." (PMID 37978469, 2023). "In human prostate cancer, S100A16 increases cell proliferation and metastasis through the AKT and ERK cell signaling pathways." (PMID 36176934, 2022). "In human prostate cancer, S100A16 promotes cell proliferation and metastasis through Akt and ERK cell signaling pathways." (PMID 36176934, 2022).
glioblastoma (5 papers, 2008 to 2025). The most malignant astrocytic tumor (WHO grade IV). "For example, S100A16 is elevated in grade I astrocytoma and S100A11 in glioblastoma." (PMID 18781180, 2008).
astrocytoma (4 papers, 2008 to 2023). "S100A16 is a recently discovered member of the S100 family obtained from astrocytoma, which is structurally more stable than other S100 genes." (PMID 34712325, 2021). "As a member of S100 proteins, S100A16 was initially isolated from astrocytomas." (PMID 37978469, 2023). "The S100A16 protein was initially isolated from a cell line derived from astrocytoma." (PMID 37978469, 2023). "S100A16 was a recent addition to the S100 family that isolated from astrocytoma." (PMID 30558666, 2018).
oral squamous cell carcinoma (4 papers, 2015 to 2023). "In MCF-7, high S100A16 accumulation supports epithelial–mesenchymal transition via the Notch-1 pathway, whereas low accumulation in oral squamous cell carcinoma patients is associated with deficient progenesis." (PMID 36613714, 2022). "This study aimed to investigate the clinical significance and functional role of S100A16 in oral squamous cell carcinoma (OSCC) suppression." (PMID 26353754, 2015). "S100A16 in comparison to S100A14, in single cooperation in oral squamous cell carcinoma, indicated that S100A16 may serve the same purpose as S100A14." (PMID 36613714, 2022).
squamous cell carcinoma (4 papers, 2015 to 2024). A carcinoma arising from squamous epithelial cells. "On the contrary, in oral squamous carcinoma, the prognosis was better for patients with high S100A16 expression suggesting that S100A16 had different buffering or inhibitory functions in adenocarcinoma and squamous carcinoma in an expression-dependent manner." (PMID 37978469, 2023). "Similar to our results, IRF6 (INF regulatory factor 6), a pro-differentiating factor which shares similar expression pattern to that of S100A16, has been shown to have a tumor suppressive activity in squamous cell carcinoma by promoting keratinocyte differentiation." (PMID 26353754, 2015). "However, besides S100A16, miR-6884-5p was reported to regulate l lncRNA LINC01224 as competitive endogenous RNA (ceRNA), and miR-6884–5p/Dishevelled segment polarity protein 3 (DVL3) axis also activated Wnt/β-catenin signaling pathway in squamous cell carcinoma." (PMID 38271114, 2024).
lymph node metastasis (3 papers, 2015 to 2025). "Overall, the expression level of S100A16 was significantly higher in those patients with lymph node metastasis." (PMID 40846689, 2025). "Co-expression of S100A14 and S100A16 was correlated with younger patient age (<60 years old,P= 0.025), lymph node metastasis (P= 0.005), ER-negative status (P= 0.008) and HER2-positive status (P < 0.001)." (PMID 25884418, 2015).
non-small cell lung carcinoma (3 papers, 2018 to 2024). A group of at least three distinct histological types of lung cancer, including non-small cell squamous cell carcinoma, adenocarcinoma, and large cell carcinoma. "High expression levels of S100A16 mRNA have been shown to be associated with poor prognosis in non-small cell lung cancer." (PMID 37509106, 2023). "For example, high levels of two S100 proteins, i.e., S100A10 and S100A16, are associated with non-small cell lung cancer (Uhlenet al., 2017)." (PMID 29904729, 2018). "The expression and functional role of S100A16 are widely studied in different histologic types of lung cancer (LC), predominantly in the non-small cell lung cancer subtypes lung adenocarcinoma (LUAD) and lung squamous cell carcinoma (LUSC)." (PMID 37509106, 2023).
Obesity (3 papers, 2014 to 2019). Accumulation of substantial excess body fat. "The recently identified S100 protein family member S100A16 has been linked with obesity, Type 2 diabetes, inflammation, and cancer, via a Ca2+-dependent mechanism." (PMID 31399502, 2019). "In our present study, we demonstrated that up-regulation of S100A16 expression in adipose tissue promoted 11β-HSD1 expression, while down-regulation suppressed 11β-HSD1 expression, suggesting S100A16 may be associated with pre-adipocyte differentiation, obesity, and insulin resistance." (PMID 31399502, 2019). "The steadily increasing epidemic of obesity continues at alarming rates, is an important public health problem, and expression changes of S100A16 and 11 β-hydroxysteroid dehydrogenase type 1(11β-HSD1) is attributable to the adipocyte differentiation." (PMID 31399502, 2019). "In our previous study, we first found a new gene, S100A16, related to obesity, which is a member of the S100 protein family." (PMID 24501224, 2014).
oral cancer (3 papers, 2013 to 2023). "This warrants investigation of p38 independent mechanisms possibly involved in S100A16 mediated modulation of differentiation markers in oral cancer cells." (PMID 26353754, 2015). "Interaction between S100A14 and S100A16 proteins was verified by co-immunoprecipitation using the oral cancer derived CaLH3 cell-line." (PMID 24086685, 2013). "Considering the role of S100A14 in oral cancer cell proliferation and invasion and its ability to regulate the expression of S100A16, it can be speculated that the S100A14\S100A16 heterodimer might have a functional significance in human cancer cells." (PMID 24086685, 2013).
pancreatic adenocarcinoma (3 papers, 2021 to 2024). "Higher expression of S100A16 in pancreatic adenocarcinoma specimens has been reported to be associated with poor patient prognosis." (PMID 37509106, 2023). "S100A16 mRNA and protein levels were found to be highly expressed in pancreatic adenocarcinoma as compared to normal tissues." (PMID 37509106, 2023). "Functionally, S100A16 overexpression has been shown to promote cell proliferation and induce the EMT phenotype and invasive potential of pancreatic adenocarcinoma cell lines both in vitro and in vivo." (PMID 37509106, 2023).
pancreatic ductal adenocarcinoma (3 papers, 2020 to 2024). An infiltrating adenocarcinoma that arises from the epithelial cells of the pancreas. "Four studies involving the differential expressions of S100A16 in the Oncomine database between Pancreatic ductal adenocarcinoma (PDAC) and normal tissues were screened." (PMID 33912559, 2021).